GLI1 (GLI family zinc finger 1)
Diseases named in the same sentence as GLI1 in open-access papers (continued):
Sharing a sentence is not in itself a finding about the gene and the disease.
lung cancer (continued). "Knocking down the expression of WW45 promoted the growth and migration of lung cancer cells, which was rescued by down-regulation of Gli1." (PMID 27661123, 2016). "Hedgehog/Gli1 signaling has been reported to be dysregulated in various cancer types, including lung cancer." (PMID 27661123, 2016). "Lung cancer cell line A427 with strong positive (+++) staining of CK2α and Gli1 was used as a positive control." (PMID 25422081, 2014). "The levels of the Hh signaling components, SHH, PTCH1, and GLI1 were significantly reduced in CDO-depleted lung cancer cells compared with the scrambled control." (PMID 25369201, 2014). "Recently, we have shown that CK2α regulates Hh/Gli1 signaling in human lung cancer, and silencing of CK2α promotes Gli1 degradation in a time-course experiment." (PMID 25422081, 2014). "First of all, the correlation of CK2 and Gli1 expressions were noticed in several lung cancer cell lines." (PMID 22768056, 2012). "Lung cancers with high cyclin E levels expressed significantly (P<0.01) higher levels of Gli1 than did cases with reduced cyclin E levels." (PMID 22923130, 2012). "Down-regulation of Gli1 expression and transcriptional activity were demonstrated after the silencing of CK2α in lung cancer cells." (PMID 22768056, 2012). "Both CK2α and Gli1 genes have been shown to be over-expressed in a variety of cancers, including lung cancer." (PMID 22768056, 2012). "Although ED-1 cells arose from transgenic lung cancers that activated the HH pathway, these cells had relatively low basal Gli1 and Gli2 mRNA levels and low basal Gli1-reporter activity." (PMID 22923130, 2012). "Aberrant hedgehog signalling has been implicated in the development of different human tumour entities such as colon and lung cancer and increased GLI1 expression has been found in these tumour entities as well." (PMID 19706168, 2009). "Furthermore, in rhabdomyosarcoma, evidence indicates a protein-protein interaction between members of mSWI/SNF (SMARCA2) and GLI-1, consistent with our findings in lung cancer, where SMARCB1 interacts with GLI-1." (PMID 39971779, 2025). "Results showed a significant decrease in EGFR, CBP, and SMARCB1 at mRNA and protein levels, and a significant increase in mRNA of EZH2, but no significant change in protein levels for EZH2, suggesting that both MEOX2/GLI-1 modulate these tumor and epigenetic markers in lung cancer A549 cells." (PMID 39971779, 2025). "Moreover, our study highlights the clinical relevance of these findings, demonstrating the increased expression of SHH, p‐STAT3, and GLI1 proteins in postosimertinib‐resistant lung cancer tissues, along with decreased DUSP13B expression." (PMID 39721017, 2025). "The Gli1-bFGF axis is crucial for the crosstalk between lung cancer cells and vascular cells." (PMID 38493151, 2024). "Our previous study showed that Glioma-associated oncogene 1 (Gli1) is a driver of NSCLC metastasis, but its role in lung cancer cell-vascular cell crosstalk remains unclear." (PMID 38493151, 2024). "Based on the postulated mechanisms, GLI1 inhibition may lead to the downregulation of its target genes, including stemness-related SOX2 and ABCG2 in lung cancer cells, thus underlying its potential therapeutic interference." (PMID 37149646, 2023). "We believe that SOX2OT acting as ceRNA to protect mRNA of METTL3/14/IGF2BP2 and guiding METTL3/14/IGF2BP2 to GLI1 mRNA is the pivotal mode of action of SOX2OT in GLI1 regulation since SOX2OT is located mainly in the cytoplasm of lung cancer cells (>85% in A549 and >70% in H1299 cells)." (PMID 37149646, 2023). "Functional analysis corroborated that GLI1 acted as a downstream target of METTL3/14/IGF2BP2, and GLI1 silencing could block the oncogenicity of lung cancer stem-like cells." (PMID 37149646, 2023). "Natural products targeting GLI1 exert potent anti-angiogenesis capability in lung cancer." (PMID 37149646, 2023). "Arsenic trioxide inhibited cancer stem-like cells via down-regulation of Gli1 in lung cancer." (PMID 37371816, 2023).
lung cancer (continued). "GLI1 is also essential for stemness-related malignancy in lung cancer." (PMID 37149646, 2023). "It has been shown to inhibit the proliferation, invasion, as well as migration of lung cancer cells and eliminates stem-like signatures by reducing the expression levels of Gli1 at both transcriptional and translational levels via inhibiting Gli1 promoter activities." (PMID 35433472, 2022). "We next analyzed the expression levels of canonical SHH signaling components—such as PTCH1, PTCH2, SMO, SUFU, and GLI1 proteins—in cultured human lung cancer cells (H1299, A549, HCC827, and H1975) and normal human lung fibroblasts (MRC-9 and WI38) by western blot analysis." (PMID 31783569, 2019). "Indeed, CK2α inhibition decreases GLI1 expression and transcriptional activity, enhancing GLI1 degradation in A549 and H1299 lung cancer cell lines." (PMID 30934935, 2019). "To determine whether the observed IL-24-mediated downregulation of GLI1 was restricted to one cell line with a stable transfection system, we performed experiments in an additional lung cancer cell line, A549." (PMID 31783569, 2019). "Hence, inhibition at the level of GLI1 will halt the endpoint execution towards cancer cell survival and proliferation, making GLI1 a promising target for lung cancer treatment." (PMID 31783569, 2019). "We next investigated whether IL-24 displays its inhibitory effect on GLI1 and its downstream targets in lung cancer cells overexpressing GLI1." (PMID 31783569, 2019). "In addition, the expression of WW45 was down-regulated in the clinical lung cancer samples, which was inversely correlated with the expression of Gli1." (PMID 27661123, 2016). "Moreover, over-expression of WW45 inhibited the tumorigenesis in a de novo lung cancer tumorigenesis mouse model (LKB-Ras) as well as the expression of Gli1." (PMID 27661123, 2016). "The increase of Gli1 protein level and Gli1 nuclear localization are very common in the lung cancer tissues, suggesting Gli1 might be a promising target for lung cancer treatment." (PMID 27661123, 2016). "Hedgehog/Gli1 signaling promotes the growth, migration and metastasis of lung cancer." (PMID 27661123, 2016). "To investigate whether JIB-04 affects GLI1 levels also under in vivo conditions, we analysed samples derived from a previously reported lung cancer cell (A549) xenograft experiment in which JIB-04 led to significant growth inhibition." (PMID 26310823, 2015). "To investigate whether CK2 is involved in the Hh pathway in human lung cancer cells, we tested the activity of Gli1 after CK2 inhibition." (PMID 22768056, 2012). "Our results suggest that CK2 is a positive regulator in Hh/Gli1 signaling in human lung cancer." (PMID 22768056, 2012). "Furthermore, two small-molecule CK2α inhibitors led to a dose-dependent inhibition of Gli1 expression and transcriptional activity in lung cancer cells." (PMID 22768056, 2012). "First, we found a correlation between CK2α and Gli1 mRNA levels in 100 primary lung cancer tissues." (PMID 22768056, 2012). "Furthermore, our results suggest that BRD9 may contribute to the activation of both lung cancer oncogenes GLI-1 and EGFR." (PMID 39971779, 2025). "Notably, BAS 07019774 inhibited the growth of GLI1-dependent glioma and lung cancer cells." (PMID 38999049, 2024). "However, whether Gli1 is involved in the intercellular crosstalk between lung cancer cells and vascular cells is still unclear." (PMID 38493151, 2024). "In addition, to establish whether HH signaling was activated in lung cancer cells, Gli1 protein levels in advanced NSCLC were assessed." (PMID 35433472, 2022). "Similar effects were seen with siRNA-GLI1 or a mixture of siRNA-MEOX2 plus siRNA-GLI1, but no significant reduction in cellular viability occurred with either anti-MEOX2 or anti-GLI-1 siRNAs in an EGFR-mutated lung cancer cell line H1975 with non-detectable MEOX2 mRNA expression." (PMID 28978016, 2017).
lung cancer (continued). "Based on this, we conducted Co-IP assays using A549 lung cancer cells, which revealed that SMARCB1 interacts with MEOX2, GLI-1, and BRD9, with a potential weak interaction with CBP and EZH2." (PMID 39971779, 2025). "In conclusion, this study reveals the critical roles of MEOX2, GLI-1, and SMARCB1 as tumor biomarkers in human lung cancer progression." (PMID 39971779, 2025). "Our study reveals how MEOX2 and GLI-1 are key molecular modulators of the GLI-1 and EGFR-epigenetic patterns, which in turn transcriptionally and epigenetically affect EGFR gene expression in lung cancer." (PMID 39971779, 2025). "Our previous study revealed that lncRNA SOX2OT exacerbated stemness features of lung cancer cells by guiding the METTL3/14 complex to facilitate m6A modification and stabilization of GLI1 RNA transcripts." (PMID 37950038, 2024). "In this study, expression level and phenotypic analyses (including proliferation and sphere formation assays) revealed that GLI1 and SOX2OT formed a positive loop to regulate the stemness of lung cancer." (PMID 37149646, 2023). "Correlation analysis indicated that the expression level of GLI1 is positively correlated to that of IGF2BP2, METTL3/14, and SOX2OT in lung cancer bulk tumor." (PMID 37149646, 2023). "The correlation of SMO, GLI1, and SOX2 expression with poor prognosis in lung cancer has been demonstrated." (PMID 37149646, 2023). "We performed data mining using the University of California Santa Cruz genome browser and Gene Expression Database of Normal and Tumor Tissues 2 (GENT2) and confirmed overexpression of SMO, GLI1, SOX2, and SOX2OT in lung cancer samples." (PMID 37149646, 2023). "Further, the SHH cascade and its executor GLI1 are aberrantly overexpressed in both CSCs and DDP-resistant lung cancer cells." (PMID 37149646, 2023). "RT-qPCR and immunoblotting revealed that SMO, GLI1, and SOX2 were more actively transcribed and translated in lung cancer spheroids than in parental cells." (PMID 37149646, 2023). "To test the expression of the GLI1/SOX2OT loop and the relevant m6A modifiers investigated in this study, we obtained a tissue chip comprising 75 pairs of lung cancer specimens and adjacent normal tissues." (PMID 37149646, 2023). "Immunohistochemistry indicated that GLI1 and METTL3/14/IGF2BP2 were significantly upregulated in lung cancer tissues compared to those in paired normal tissues." (PMID 37149646, 2023). "Meanwhile, the mRNA and protein expressions of Shh, Smo, Gli1 and PHC3 were highly activated in CD133+ lung cancer cells." (PMID 34424425, 2021). "Studies have shown that among the three human GLI factors, GLI1 and GLI2 are crucial for the development and progression of many human cancers, including lung cancer." (PMID 31783569, 2019). "In this study, we have found that WW45 was dramatically down-regulated in clinical lung cancer tissues and established cell lines, and WW45 inhibited the activation of Hedgehog/Gli1 signaling by promoting the ubiquitination of Gli1." (PMID 27661123, 2016). "On the other hand, it has been proposed that glycogen synthase kinase-3 beta negatively regulates Gli1 transcription factors cooperating with other kinases such as PKA and CK1s in lung cancer A549 cells." (PMID 22768056, 2012). "While high IGFBP6 levels were present in some lung tumors, it is notable that lung cancers with both high cyclin E and reduced IGFBP6 expression significantly (P<0.0001) increased Gli1 expression." (PMID 22923130, 2012). "Our findings contrast with previous studies in lung cancer patients, where those with low GLI-1 expression showed significantly better progression-free survival with EGFR-TKI erlotinib treatment compared to those with high GLI-1 expression." (PMID 39971779, 2025). "Furthermore, this study suggests that epigenetic regulators, including the NuRD (MTA2) and ncBAF (BRD9) complexes, contribute to EGFR and GLI-1 expression and interact with MEOX2 in lung cancer cells." (PMID 39971779, 2025).
lung cancer (continued). "In conclusion, our results suggest novel molecular mechanisms whereby MEOX2 and GLI-1 may modulate functional dynamics between cBAF (SMARCB1) and ncBAF (BRD9) complexes, contributing to lung cancer progression." (PMID 39971779, 2025). "GLI1, expressed by 76% of lung cancers, can be noncanonically activated by Nrp2/VEGF-mediated MAPK/ERK signaling, and silencing GLI1 attenuates cancer cell stemness and proliferation, and increases their susceptibility to apoptosis." (PMID 38592275, 2024). "Accumulated GLI1 activated SOX2/SOX2OT transcription by interacting with their promoter, ensuring positive self-regulation and consistent activation of the GLI1-SOX2OT loop in lung cancer cells." (PMID 37149646, 2023). "In lung cancer, SAV1 could bind to zinc finger protein Gli1 and negatively regulate the Hedgehog signaling pathway." (PMID 37033161, 2023). "To further explore whether SFN regulated SHH signaling pathway and PHC3 in lung CSCs, we examined the effects of SFN on the mRNA expression level of Shh, Smo, Gli1 and PHC3 in CD133+ lung cancer cells." (PMID 34424425, 2021). "SFN could also inhibit protein expression of Shh, Smo, Gli1 and PHC3 in the lung cancer stem cells (P < 0.01or P < 0.001)." (PMID 34424425, 2021). "This suggests a probable positive transcriptional biofeedback between GLI-1 mRNA and protein on lncRNA GLI1AS expression on epithelial origin tumors, the latter probably epigenetically involved in cancer therapy resistance, including lung cancer." (PMID 28904641, 2017). "In addition, SFN inhibited the activities of Shh, Smo, Gli1 and PHC3 in CD133+ lung cancer cells." (PMID 34424425, 2021). "However a non-canonical GLI-1 activation likely occurs in a Rack1-dependent manner in NSCLC patients as a proposed necessary step for lung cancer tumorigenicity." (PMID 28978016, 2017). "Subsequently, this positive co-expression among both low and high protein expression lung cancer patient groups was quantitatively detected in the INCAN patient cohort by undertaking an Intensity Index analysis based on Algorithm Positive Pixel Bin Counts for MEOX2 and GLI-1." (PMID 28978016, 2017). "Furthermore, survival curve analysis of all INCAN lung carcinoma patients with EGFR-non-mutated status identified a better overall survival index (statistically significant at p≤0.005) with lower MEOX2 and GLI-1 protein expression levels (p=0.122 and p=0.002, respectively)." (PMID 28978016, 2017). "The data disclose a new GLI1 stimulation pathway independent of the SHH/PTCH/SMO cascade and offer new insights into the stemness-related malignancy of lung cancer cells." (PMID 37149646, 2023).
Ewing sarcoma (31 papers, 2009 to 2025). A small round cell tumor that lacks morphologic, immunohistochemical, and electron microscopic evidence of neuroectodermal differentiation. "For example, the EWS/FLI translocation driver of Ewing’s sarcoma directly transactivates de GLI1 promoter." (PMID 36765685, 2023). "GLI-1 knockout significantly reduces Akt phosphorylation in Ewing’s sarcoma cells, and this effect can be salvaged by the overexpression of GLI-1 and KRT17." (PMID 35281081, 2022). "In Ewing’s sarcoma, KRT17 is the downstream expression gene of the glial-associated oncogene homologue 1 (GLI-1), which positively regulates KRT17 expression." (PMID 35281081, 2022). "GLI1 represents an important driver gene of proliferation and spheroid growth in Ewing sarcoma cells." (PMID 34439381, 2021). "To corroborate that CSNK1D inhibition is a potent strategy to block GLI activation in SMOi-resistant settings, we performed chemical inhibition of CSNK1D in A673 and MHH-ES-1 Ewing sarcoma cells both showing SMO-independent GLI1 expression." (PMID 34439381, 2021). "Regarding bone sarcoma, it has been established that Gli1 is a direct transcriptional target of EWS-Fli1 in Ewing Sarcoma." (PMID 32110934, 2020). "We chose Ewing sarcoma because this tumour type was shown to directly dependent on GLI1 and knockdown or inhibition of GLI1 exerts antineoplastic effects in this cancer." (PMID 31492956, 2019). "These authors also confirmed using RNAi that the expression of GLI1 in Ewing sarcoma cells (TC71) is dependent on EWS/FLI1 and that GLI1 expression was relevant for the maintenance of the transformed phenotype." (PMID 26258070, 2015). "The fact that GLI1 expression is constitutively induced by EWS/FLI1 in Ewing sarcoma suggests that drugs acting upstream GLI1 will be ineffective in blocking this pathway in this cancer." (PMID 26258070, 2015). "Moreover, when a short hairpin RNA (shRNA) designed to target GLI1 was applied to the Ewing sarcoma cell line TC32, it led to the inhibition of the transformed phenotype." (PMID 37894854, 2023). "Additionally, when a short hairpin RNA (shRNA) targeting GLI1 was employed in the Ewing sarcoma cell line TC32, it resulted in the inhibition of the transformed phenotype, as evidenced by a reduction in anchorage-independent growth." (PMID 37894854, 2023). "Interestingly, in contrast to the usual findings in other cancer types, the abnormal regulation of GLI1 in Ewing sarcoma occurs independently of Sonic Hedgehog (Shh) signaling." (PMID 37894854, 2023). "Arsenic trioxide (ATO) (IC50: 2.7 μM), approved by the FDA for acute promyelocytic leukemia (APL), targeted the Gli1 transcription factor and exhibited significant cytotoxicity in mice models of MB and Ewing sarcoma, supporting further pharmacological evaluation in Gli1-dependent malignancies." (PMID 35433472, 2022). "In rhabdomyosarcoma and Ewing sarcoma, GLI1 is upregulated and contributes to drug resistance." (PMID 33906647, 2021). "However, this chemical was also identified as an inhibitor of the transcriptional activity of Gli1/-2 in Ewing sarcoma." (PMID 32110934, 2020). "Importantly, in TC71 and RDES Ewing sarcoma cells, combined PI3Kα and mTOR inhibition resulted in reduced nuclear GLI1." (PMID 31492956, 2019). "Ewing sarcoma cells harboring the EWS-FLI1 oncogenic fusion gene have been shown to express GLI1 in response to direct binding of the EWS-FLI1 oncoprotein to the GLI1 promoter." (PMID 26784250, 2016). "We also found that JQ1 significantly downregulated expression of GLI1 in Ewing sarcoma cells." (PMID 27259270, 2016). "Moreover, when a shRNA against GLI1 was used in the Ewing sarcoma cell line TC32, the transformed phenotype was inhibited (measured by reduction in anchorage independent growth)." (PMID 26258070, 2015). "Our work with the GLI1 inhibitor GANT58 suggests that this pathway may be a valid target for translational research in Ewing Sarcoma." (PMID 19859563, 2009).